ADAMTS12 (ADAM metallopeptidase with thrombospondin type 1 motif 12)
Diseases named in the same sentence as ADAMTS12 in open-access papers (continued):
Sharing a sentence is not in itself a finding about the gene and the disease.
tumor (53 papers, 2011 to 2025). "Certain ADAMTS proteins, such as ADAMTS1 and ADAMTS12, have been implicated in angiogenesis, the formation of new blood vessels that support tumor growth." (PMID 38339175, 2024). "Other researchers also observed that TTN, OBSCN, and ADAMTS12 genes were frequently mutated in cfDNA WES although tumor types are different as HCC." (PMID 35402275, 2022). "We assessed the expression, clinical characteristics, prognostic significance, copy number alteration, methylation, and mutation of ADAMTS12 and its correlation with the tumor immune microenvironment." (PMID 35280819, 2022). "The association between ADAMTS12 expression, the tumor immune microenvironment (TIME), was also assessed." (PMID 35280819, 2022). "On the other hand, the phenotypic analysis of the Adamts12 deficient mouse indicated that this protein plays a protective role against angiogenesis and tumor growth." (PMID 33996918, 2021). "Regarding tumor-related processes, ADAMTS-12 has also been implicated to have a dual effect, described as a protumor factor as well as an antitumor factor." (PMID 31508361, 2019). "By contrast, several studies have highlighted the anti-tumor role of this metalloprotease, including the phenotypic characterization of Adamts12-deficient mouse." (PMID 24457941, 2014). "Malignant keratinocyte (PDVA cell line) transplantation demonstrated that tumor vascularization and invasion were increased in ADAMTS-12-deficient-mice." (PMID 24876675, 2014). "Phenotypic analysis of the Adamts12-deficient mouse has confirmed the tumor-protective role of this enzyme." (PMID 24457941, 2014). "Remarkably, this epigenetic silencing in the tumor cells is associated with a concurrent overexpression of ADAMTS-12 in the stromal compartment where it exerts an anti-angiogenic effect." (PMID 22822400, 2012). "ADAMTS12 has been found to be associated with the malignant behaviors of tumor cells." (PMID 38167385, 2024). "Different mechanisms may cause the anti-tumor effects of ADAMTS-12." (PMID 24457941, 2014). "In vivo studies further confirmed that the inhibition of ADAMTS12 effectively suppressed tumor progression." (PMID 39761856, 2025). "Regarding cancer, ADAMTS-12 was initially described to show an anti-tumor effect in Madin Darby canine kidney (MDCK) cells by inhibition of the Ras-MAPK signaling pathway." (PMID 38396702, 2024). "Compared with the oe-NC + PBS group, ADAMTS12 overexpression accelerated tumor growth and increased tumor volume and weight, and treatment with metformin alone restrained tumor growth." (PMID 38167385, 2024). "But the concomitant treatment of metformin and ADAMTS12 overexpression slowed the stimulatory effects on tumor growth, volume, and weight." (PMID 38167385, 2024). "Conversely, ADAMST12 deficiency leads to an enhanced angiogenic response and increased tumor invasion, as demonstrated by in vitro and in vivo studies, suggesting that ADAMTS12 is a possible antitumor factor." (PMID 38167385, 2024). "In conclusion, these data confirmed that metformin repressed GC tumor growth in vivo by modulating ADAMTS12." (PMID 38167385, 2024). "The expression of the ADAMTS12 gene was also compared between normal and tumor tissue, revealing differences between these two materials." (PMID 38339175, 2024). "Based on data collected from the UALCAN database, differences in the ADAMTS6, ADAMTS9 and ADAMTS12 gene expression levels were also assessed between tumor tissue and normal tissue." (PMID 38339175, 2024). "The second aim of the project was to evaluate the expression of the ADAMTS6, ADAMTS9 and ADAMTS12 genes in the tumor tissue samples." (PMID 38339175, 2024). "A survival analysis was conducted based on the ADAMTS6, ADAMTS9 and ADAMTS12 expression in tumor tissue using data gathered from the external Kaplan–Meier Plot database." (PMID 38339175, 2024).
tumor (continued). "The higher FIGO stage was the result of tumor progression, which is consistent with the conclusion that ADAMTS12 levels increase with tumor progression, suggesting that ADAMTS12 has the potential to predict tumor progression." (PMID 37642715, 2023). "In this study, we assessed the expression of ADAMTS12 and found it to be elevated in 13 out of 33 tumor types compared with normal tissues." (PMID 35280819, 2022). "From the GSEA-KEGG analysis, ADAMTS12 was observed to be enriched in most tumor-promoting pathways, including the “Hippo signaling pathway,” the “PI3K-Akt signaling pathway,” and the “JAK-STAT signaling pathway”." (PMID 35280819, 2022). "While ADAMTS12 has also been reported to affect the inflammatory response of pancreatitis, and also act as a tumor suppressor gene in lung adenocarcinoma." (PMID 35280819, 2022). "Among tumor tissues from TCGA, we found that ADAMTS12 expression was highest in PAAD and lowest in LAML." (PMID 35280819, 2022). "Our results suggest that ADAMTS12 expression was higher in relatively worse tumor stages in ACC, BLCA, ESCA, HNSC, MESO, PAAD, STAD, and THCA." (PMID 35280819, 2022). "To evaluate the prognostic significance of ADAMTS12, we performed UniCox and Kaplan-Meier analyses in 33 tumor types." (PMID 35280819, 2022). "Analysis of associations between biomarkers and tumor grading revealed statistically significant differences in promoter hypermethylation of RASSF1, ADAMTS12 (G1 vs. G2), and MT1E (G2 vs. G3) (p < 0.05)." (PMID 36499753, 2022). "High expression level of ADAMTS12 was correlated with worse survival rates in patients with PAAD and high infiltration levels of tumor-associated macrophages, cancer-associated fibroblasts, immune checkpoint proteins, and immunosuppressive genes." (PMID 35280819, 2022). "A recent study revealed that ADAMTS12 was highly expressed in the PDAC stroma, which was closely associated with tumor progression." (PMID 35047000, 2021). "Further analysis showed that ADAMTS12 expression was significantly higher in tumor samples and correlated with poor prognosis." (PMID 34040054, 2021). "ADAMTS-12 has also been involved in cancer development acting either as a tumor suppressor or as a pro-tumoral agent." (PMID 33996918, 2021). "The high expression rate of ADAMTS12 in GC was 93.3% (28/30) (Tumor/Normal > twofold), with up to 23-fold increases in cancer tissues." (PMID 34040054, 2021). "The high-risk group had a higher tumor mutational burden (TMB) (p < 0.05), with significantly higher mutation frequencies in KRAS and ADAMTS12 (p < 0.05)." (PMID 35047000, 2021). "Consistent with the transcriptome data, the protein expression of 4 genes (IGF2BP1, IGF2BP3, HMMR and ADAMTS12) were up-regulated in LUAD tumor samples." (PMID 34721973, 2021). "The ADAMTS12 is a novel anti-tumor metalloprotease, and the expression is epigenetically silenced in tumor cells." (PMID 34721973, 2021). "Therefore, ADAMTS12 may be linked to tumor energy metabolism." (PMID 34040054, 2021). "And second, an overexpression of ADAMTS-12 by the fibroblasts surrounding neoplastic cells was detected, which suggest a protective stromal response to reduce tumor progression." (PMID 33996918, 2021). "Wilcoxon rank sum test illustrated that the ADAMTS12 expression level in tumor group was significantly higher than that in normal group." (PMID 34040054, 2021). "We have provided evidence of the tumor-suppressor role of ADAMTS12 in this cancer type both in vitro and in vivo." (PMID 32732999, 2020). "We show that ADAMTS12−/− mice have a five-fold increase in the susceptibility to develop lung tumors, confirming the role of ADAMTS12 as a tumor suppressor gene." (PMID 32732999, 2020). "ADAMTS12 is a member of the disintegrin and metalloproteinase with thrombospondin repeats gene family reported to be endowed with a tumor protective role in several studies." (PMID 29503225, 2018).
tumor (continued). "Exploring the mechanisms that link ADAMTS-12 to tumorigenesis would help to minimize pro-tumor properties and thereby enhance anti-tumor effects of this metalloprotease." (PMID 24457941, 2014). "On this basis we searched for molecular partners of ADAMTS-12, a secreted metalloprotease that shows both oncogenic and tumor-suppressive effects." (PMID 24457941, 2014). "Contrary to this, we had previously found that exogenous expression of ADAMTS12 in A549 cells inhibited tumor growth in vivo." (PMID 24457941, 2014). "Further investigation revealed that this discrepancy was due to the overexpression of ADAMTS12 in stromal cells that are in vicinity of the tumor cells." (PMID 24213506, 2012). "The Adamts-12 promoter is hypermethylated in cancer cell lines and tumor tissues leading to reduced production of ADAMTS-12 that exerts anti-tumorigenic effect." (PMID 22822400, 2012). "Although this study did not specifically address cell invasion, it did shed light on the importance of how ADAMTS-12 in the tumor microenvironment inhibits key aspects of tumorigenesis, such as cell proliferation and angiogenesis." (PMID 21494557, 2011). "Recent studies characterizing the role of ADAMTS-12 in tumor progression demonstrated an anti-tumorigenic role for this subtype." (PMID 21494557, 2011). "Reducing the expression of the ADAMTS12 gene in lung cells affected by cancer resulted in increased cell proliferation and invasiveness, indicating that ADAMTS12 may act as a tumor suppressor gene." (PMID 39940703, 2025). "It is tempting to speculate that upregulation of ADAMTS12 in fibroblasts could be induced by cancer cells during the early stages of tumour development, while at later stages more aggressive cancer cells prevent stromal accumulation of ADAMTS12." (PMID 38948119, 2024). "ADAMTS12 level was strongly correlated with tumor stage (P = 0.007)." (PMID 37642715, 2023). "At the same time, we found that the ADAMTS12 level increased as tumor stage progressed." (PMID 37642715, 2023). "For example, the results of mass spectrometry were not verified by the WB experiment, and whether the glycosylation of ADAMTS12 protein affects the biological function of tumor will be our possible direction of follow-up research." (PMID 37642715, 2023). "In terms of tumor, the potential biological properties of ADAMTS12 are various in different tumors." (PMID 37642715, 2023). "The in vitro study identified miR-186 as a tumor suppressor in BCa by binding to ADAMTS12." (PMID 37092087, 2022). "It has been suggested that ADAMTS12 may be a promoter of GI tumors, responsible for tumor microenvironmental status and tumor energy metabolic transition." (PMID 35646642, 2022). "We further assessed ADAMTS12 expression in various tumor stages." (PMID 35280819, 2022). "The authors speculated that the upregulation of ADAMTS12 in the stroma may be a response to restrain the growing ADAMTS12-negative tumor." (PMID 34268335, 2021). "In particular, IL6 and BST2 were significantly induced in all naïve MSCs after 3 days’ coculture with primary tumor cells, whereas the expressions of ADAMTS12, MX2, LOXL2 and GREM1 varied and displayed transient induction during the course of the coculture assay." (PMID 34513701, 2021). "Initially, ADAMTS-12 was described as a tumor suppressor protein, as the exogenous expression of ADAMTS-12 in Madin-Darby Canine Kidney (MDCK) cells prevents the phenotypic changes associated with renal carcinogenesis caused by the growth factor of hepatocytes (HGF)." (PMID 33996918, 2021). "ADAMTS12 may also play a role in the tumor process owing to its proteolytic activity or serve as a potential molecule involved in the regulation of cell adhesion." (PMID 32884571, 2020). "A previous study revealed that ADAMTS12 has anti-tumor-growth and angiogenesis effects." (PMID 32884571, 2020).
tumor (continued). "Consequently, a decrease in expression levels of ADAMTS-12 in more advanced stages of the disease, such as those analyzed in this work, would contribute to the spreading of tumor cells." (PMID 28099917, 2017). "Indeed, several studies have showed that anti-tumor effects of ADAMTS8 and ADAMTS12 are closely associated with the suppression of ERK signaling." (PMID 28145888, 2017). "Our new data support that the protection that ADAMTS-12 exerts on Fibulin-2 degradation by aggrecanases might form part of a defensive response against tumor invasion by strengthening the physical barrier created by Fibulin-2 and its interacting partners." (PMID 28099917, 2017). "The actual secretion of ADAMTS-12 was lost by the epigenetic silencing in tumor cells." (PMID 24876675, 2014). "Furthermore ADAMTS-12 inhibited tumor growth in vivo as well, since injection of A549 cells overexpressing ADAMTS-12 into the immunodeficient-SCID-mice showed a reduced tumor growth." (PMID 24876675, 2014). "In consequence, pro or anti-tumor activities of ADAMTS-12 could also be influenced by factors other than interaction with fibulin-2." (PMID 24457941, 2014). "ADAMTS12 has been confirmed to be expressed in a variety of human tissues and plays a significant role in the pathological process of various diseases, such as tumor, inflammation, arthritis, intervertebral disc degeneration, angiogenesis, schizophrenia, and gonadal development." (PMID 37642715, 2023). "Although these analyses suggest that ADAMTS12 levels may predict tumor malignancy, it cannot be determined whether ADAMTS12 is directly related to tumor malignancy or indirectly related to tumors due to factors such as stage, differentiation, and adjuvant chemoradiotherapy." (PMID 37642715, 2023). "Hence, through further research on ADAMTS12, a new understanding of the potential relationship between tumor microenvironment and GC prognosis could be achieved." (PMID 34040054, 2021). "In addition, ADAMTS12 gene is epigenetically silenced by hypermethylation of its promoter in tumors of different sources, which reinforced the hypothesis of ADAMTS12 as a tumor suppressor." (PMID 33996918, 2021). "However, the effect of ADAMTS12 on the tumor microenvironment needs to be further elucidated." (PMID 35047000, 2021). "However, ADAMTS12 is considered as a tumor suppressor in other cancers." (PMID 32908454, 2020). "Thus, ADAMTS-12 may provide a new molecular target for treating various types of cancer in addition to the potential of being employed as a prognostic indicator in tumor malignant grade and metastasis." (PMID 24876675, 2014). "In addition, ADAMTS-12 may function as a tumor suppressor through limiting the proliferation of tumor cells." (PMID 24876675, 2014). "Thus, it can be speculated that exogenous ADAMTS-12 may interact with fibulin-2 produced by A549 cells and thereby inducing the anti-tumor effect observed." (PMID 24457941, 2014). "The tumor-suppressive mechanism of some ADAMTS family members, such as ADAMTS8 and ADAMTS12, is manifested by antagonizing ERK signaling, and the ERK/P38 MAPK signaling pathway inhibits tumor growth in colon adenocarcinoma." (PMID 38482210, 2024). "For instance, even if ADAMTS12 has been found silenced in CRC cells, its expression was higher in stromal cells surrounding the tumour." (PMID 38948119, 2024). "Remarkably, ADAMTS12 was found to bind to fibulin-2 and protect it from being degraded by ADAMTS4 and 5, showing a tumour suppressive behaviour." (PMID 38948119, 2024). "Consistently, the expression of ADAMTS12 prevented ADAMTS5-induced invasion in vitro and opposed tumour growth in vivo in xenograft experiments in nude mice." (PMID 38948119, 2024). "For ADAMTS12, AEBP1, COL10A1, COL11A1, CXCL11, EPPK1, and WNT7B, their expression values were higher in tumor samples than in normal samples." (PMID 35505821, 2022).
tumor (continued). "We also assessed the prognostic value of ADAMTS12 in disease-specific survival (DSS), disease-free interval (DFI), and progression-free interval (PFI) of tumor patients using UniCox analysis." (PMID 35280819, 2022). "It was also shown that tumor cells alone can modulate the gene expression profile of naïve MSCs, including IL-6, BST2, ADAMTS12, MX2, LOXL2 and GREM1." (PMID 34513701, 2021). "Reconstitution of N-MSCs with four genes, GREM1, LOXL2, ADAMTS12 and ITGA11 that contributed to the T-MSC phenotype increased their ability to promote primary tumor cell dissemination." (PMID 29503225, 2018). "Conversely, TGF-β abrogated tumor cell-co-culture-dependent augmentation of LOXL2 and ADAMTS12 expression in patient 21 N-MSCs (right column)." (PMID 29503225, 2018). "However, studies have suggested that the tumor-suppressive effects of ADAMTSs are linked to the deactivation of proliferation or invasion pathways, including inhibition of the ERK pathway by ADAMTS8, ADAMTS12, and ADAMTS15; and of the AKT/mTOR pathway by ADAMTS9." (PMID 27542224, 2016). "To elucidate the molecular pathways and functions of ADAMTS12 in BCa, we employed various experimental approaches, including Transwell invasion assays, flow cytometry analysis, wound-healing assays, CCK-8 assays, and a xenograft tumor model." (PMID 39761856, 2025). "In addition, ADAMTS12 is highly expressed in GC and responsible for tumor microenvironment (TME) status and tumor energy metabolism and transformation, acting as a TME-related cancer promoter." (PMID 38167385, 2024). "In cancer-related processes, ADAMTS12 shows dual effects, being pro and anti-tumor in a proteolytic or non-proteolytic manner." (PMID 37240178, 2023). "According to the current findings, ADAMTS12 exhibits dual pro- and/or anti-tumor effects in proteolytic or non-proteolytic pathways." (PMID 37092087, 2022). "We further revealed that ADAMTS12 expression was positively correlated with immune checkpoint proteins (such as PDCD1, CD274, LAG3, and CTLA4), immunosuppressive genes, chemokines, and chemokine receptors in most tumor types." (PMID 35280819, 2022). "In cancer-related processes, ADAMTS12 shows dual effects of pro and/or anti-tumor in a proteolytic or non-proteolytic manner." (PMID 34040054, 2021). "ADAMTS-12, like many other members of the ADAMTS family, may have a pro- or anti-tumor role in various types of cancers." (PMID 33996918, 2021). "In order to illustrate the relevance between ADAMTS12 expression and immune microenvironment, CIBERSORT computational method was implemented to analyze the proportion of immune subpopulations in tumor infiltration, and the map of 22 immune cells in GC samples was constructed." (PMID 34040054, 2021). "When there was no immune infiltrate in PAAD, 8 ADAMs had a different expression with no significance, except ADAMTS12 that was negatively related to purity state of tumor cell." (PMID 33062410, 2020). "ADAMTS12, is classified as proteinase of the cartilage oligomeric matrix protein (COMP), it is inducing neutrophil apoptosis in mice, and silenced ADAMTS12 genes were found in human tumor cells." (PMID 32817637, 2020). "By using a model of induced tumors after malignant keratinocytes transplantation, the absence of ADAMTS-12 in Adamts12−/− mice results in an increase in the angiogenic response and in tumor growth when compared with wild type mice." (PMID 31508361, 2019). "Taking into account these results, it could be hypothesized that ADAMTS-12 protects Fibulin-2 from the degradation mediated by ADAMTS-5, which could influence the equilibrium between tumor-promoting and tumor-preventing functions attributed to Fibulin-2." (PMID 28099917, 2017). "In the absence of ADAMTS-12, both the angiogenic response and tumor invasion into host tissue are increased." (PMID 22822400, 2012).